C3 (complement C3)
Diseases named in the same sentence as C3 in open-access papers (continued):
Sharing a sentence is not in itself a finding about the gene and the disease.
glaucoma (36 papers, 2013 to 2025). Increased pressure in the eyeball due to obstruction of the outflow of aqueous humor. "Complement factor 3 (C3) is recognized as a key marker for neuroinflammation in many neurodegenerative diseases, and has recently been implicated in glaucoma." (PMID 39201471, 2024). "It has been suggested that, at an early stage of a mouse glaucoma model, the complement cascade mediates synapse loss, in particular C3." (PMID 33799827, 2021). "In the current datasets, optic nerve head monocyte-like cells highly express various complement genes (including C1qa, C1qb, C1qc, C3, and C3ar1), and complement activation is implicated in human glaucoma." (PMID 30670050, 2019). "However, although inhibition of C3 appeared protective to the aging brain, deficiency of C3 exacerbated some phenotypes in mouse models of AD and glaucoma." (PMID 32273396, 2020). "Using the microbead-induced mouse model of glaucoma, we also show an induction of genes associated with each of these pathways at 4 weeks post-microbead injection, specifically C3 and C1Q (complement cascade), TLR4 (Toll-like receptor pathway), TNFα (TNFα pathway), and NLRP3 (inflammasome pathway)." (PMID 31570110, 2019). "Enhancement of several complement factors including C1q, C3, C5 and membrane attack complexes have been observed in glaucoma patients and in animal models of glaucoma." (PMID 39104531, 2024). "In this paper, we aimed to develop a novel gene therapy for glaucoma using an AAV2-based thioredoxin 2 (Trx2)-exoenzyme C3 transferase (C3) fusion protein expression vector (scAAV2-Trx2-C3)." (PMID 38003443, 2023). "Increased deposition of complement component 1Q (C1q) and 3 (C3) in particular have demonstrated to be well conserved inflammatory signals across animal models and human glaucoma samples." (PMID 35986368, 2022). "Based on two outstanding PE-associated pathways, including glaucoma and PE, identified by GSEA, ten key genes, including IGFBP1, CORIN, and C3, were revealed." (PMID 35647297, 2022). "During acute or chronic inflammation, overexpression of C3 is known to occur not only in glaucoma but also in other eye diseases like AMD or DR." (PMID 34943212, 2021). "AAV-mediated intravitreal delivery of a CR2-Crry construct, which inhibits all complement pathways at C3 activation, provides neuroprotection to RGCs in murine models of glaucoma and MS." (PMID 33072106, 2020). "We demonstrate elevated C3 production following A1 activation and decreased C3 production following NLY01 inhibition in our glaucoma model." (PMID 33147455, 2020). "Complement component C1q is known to be upregulated in the retina during glaucoma, and upregulation of C1q and C3 expression is an early event in the development of glaucoma in mice." (PMID 33072106, 2020). "As the complement system has been shown to be involved in synaptic elimination both during development and in pathological situations such as glaucoma or sciatic nerve injury, we determined the expression levels of the complement components C1q and C3." (PMID 23936241, 2013). "There is at most a hint to the alternative pathway in complement activation due to the increased level of C3 in glaucoma (p = 0.02)." (PMID 23451242, 2013). "However, a study using an ocular hypertensive model for glaucoma found the opposite effect, where C3 was protective in that model; instead, protein complement C1q was considered by the authors to be neurodegenerative to RGCs." (PMID 40076480, 2025). "In this study, the levels of C3a and C3 were measured in the aqueous humor and serum of glaucoma and control (cataract) patients, and a significant increase in the C3a/C3 ratios in the aqueous humor and serum was only found in POAG patients with progressive disease." (PMID 38396986, 2024).
glaucoma (continued). "Interestingly, in older women (≥60 years) with primary angle-closure glaucoma (PACG), a higher risk of progressive visual field loss was found to be significantly associated with decreased serum levels of C3, C4, and C1Q at baseline." (PMID 38396986, 2024). "Upregulated C3 levels in the AH of African Americans could be one of the factors posing higher risks for glaucoma severity, with subsequent complement cascade activation triggering the proteolytic cleavage of C3 into C3a and C4b." (PMID 37763167, 2023). "Elevated levels of C1q, C3, and C5b-9 were also noted in the retina of patients with glaucoma." (PMID 35566463, 2022). "C3, as a member of the complement cascade, is strongly involved in glaucoma disease." (PMID 34944083, 2021). "Complement C3 activation intersects the three pathways of complement activation, and one group assessed an AAV vector encoding a C3 inhibitor, CR2-Crry (AAV2-CR2-Crry), in the DBA/2J mouse model of glaucoma." (PMID 33920974, 2021). "We quantified the majority of key proteins associated with classical complement pathway, such as C1q, C1s, C1r, C4a, C4b, C3, C5, C6, C7, C8a, C8b, C8g and C9, as up-regulated in glaucoma condition for both vitreous and retinal tissues when compared to the controls." (PMID 28978942, 2017). "In the DBG model, complement component 3 (C3) expression in ONH astrocytes increases gradually from 9–10 months to 12 months of age, suggesting a sustained role in glaucoma progression." (PMID 41146424, 2025). "While the complement C3 was only increased in CTGF and CTGF+ONA retinae, enhanced numbers of the terminal membrane attack complex were noted in all three glaucoma groups." (PMID 38515755, 2024). "While more C3+ cells were also solely noted in CTGF and CTGF+ONA retinae, a higher number of MAC+ cells was observed in all three glaucoma groups." (PMID 38515755, 2024). "A total of 11 unique protein-coding genes posterior probability (PP) of H4 > 0.70 finally remained, including GSTM3 for senile cataract, WARS1, C3, IGFBP7, and PILRA for AMD, ECI1, LCT, and NPTXR for glaucoma, EFEMP1 for myopia, and SIRPG and SIGLEC14 for DR." (PMID 39408566, 2024). "In the present study, we detected the formation of proinflammatory microglia/macrophages and neurotoxic astrocytes, deposition of complement C3, and production of proinflammatory cytokines (TNF and IL-1β) in the rat glaucoma model we previously used." (PMID 35132339, 2022). "A1 astrocytes upregulate C3, and C3 inhibitors were shown to reduce RGC cell death in the DBA/2J mouse model of glaucoma." (PMID 33147455, 2020). "Therefore, it is not surprising that, in addition to an upregulation of C1q, an upregulation of C3 in ONH and retina is also detected in multiple animal models of glaucoma." (PMID 38396986, 2024). "For instance, C1qa and C3 have been shown to be necessary for synaptic pruning in the retina during development, and may be necessary for RGC synapse remodeling early in glaucoma." (PMID 23806181, 2013). "However, knocking out C3 in the DBA/2J mouse model of glaucoma was not neuroprotective, but rather exacerbated the disease process." (PMID 38396986, 2024). "Supporting an involvement of the complement system in glaucoma, in IOP-independent experimental autoimmune glaucoma model (EAG) an increase of C3 positive cells and an increase of C3 mRNA level could be found 14 days after induction, while the C5 level remained unchanged." (PMID 34943212, 2021). "In addition, systemic alterations of complement component 3 (C3) were also identified in PACG patients, with significantly lower plasma C3 levels in PACG when compared to controls, especially in older women, suggesting a role of this protein in the etiology and/or progression of glaucoma." (PMID 34439995, 2021).
glaucoma (continued). "Furthermore, C3 levels increased 1.21-fold in African American POAG patients compared to those with cataracts, whereas decreased levels were detected in Caucasians with POAG, suggesting that there is perhaps a race-dependent role of the alternative complement pathway in glaucoma." (PMID 37763167, 2023).
kidney damage (36 papers, 2012 to 2026). "It should also be noted that elevated serum levels of complement C3 have also been related to an increased risk of developing diabetic retinopathy, nephropathy, and neuropathy, through endothelial dysfunction and thrombosis." (PMID 33804977, 2021). "The majority of the studies that have examined the association between complement C3 levels and nephropathies have been conducted in adults." (PMID 30003098, 2018). "In FHR-5 nephropathy the mutated FHR-5 protein is thought to promote C3 activation along surfaces within the kidney, by interfering with the ability of FH to negatively regulate glomerular complement by out-competing FH for binding to glomerular C3 (FH deregulation)." (PMID 34193601, 2021). "Furthermore, studies suggest that MBL, H-ficolin, C3 complement component and the membrane attack complex could be involved in causing kidney damage in a high blood sugar setting." (PMID 39319258, 2024). "Animal studies support these observations, showing that anti-MPO IgGs induce kidney damage with C3 deposits, while complement-depleted mice are protected from kidney damage." (PMID 38445024, 2024). "Together with other nephropathy indicators such as proteinuria, blood pressure, blood C3 levels and renal pathology, we will further investigate the potential of C3aR and the NLRP3 inflammasome as diagnostic and prognostic markers of CKD." (PMID 38082306, 2023). "In the antagomir group, urinary protein levels and C3 IF deposition in the kidneys were increased, and kidney damage was more serious, which is consistent with results from a previous report." (PMID 34668631, 2021). "And C3 positivity on renal histopathology correlated with severer kidney damage, whereas blockage of C3 signaling improved renal outcomes in various DN animal models." (PMID 32685522, 2020). "The pathogenesis of LN is due to a loss of immune self-tolerance and subsequent polyclonal antibody activation characterized by full-house nephropathy (concurrent positive staining for IgM, IgA, IgG, C1q, and C3 by immunofluorescence) and positive ANA." (PMID 33644084, 2020). "Pegcetacoplan is a targeted C3 and C3b inhibitor mitigating complement-mediated kidney damage." (PMID 41155921, 2025). "Moreover, the decrease of serum C3 level can also reflect the degree of kidney damage in IgAN patients to a certain extent." (PMID 38204800, 2024). "When compared to conventional markers of disease activity (anti-dsDNA antibody and C3 levels) and kidney damage (proteinuria, serum creatinine and renal SLEDAI-2K score), CD44 level showed a better correlation with eGFR, and comparable correlation with serological and clinical parameters of disease." (PMID 39411720, 2024). "It has been speculated that there is complement during the formation of IgAN crescents and that serum IgA/C3 ratio reflects the degree of pathological kidney damage." (PMID 37667217, 2023). "C3 deposition of the glomerular capillary wall can be shown by immunofluorescence, which is consistent with the assumption that complement activation participated in the generation of kidney damage of human anti-GBM disease." (PMID 35874697, 2022). "The prevailing hypothesis to explain the development of excessive glomerular C3 deposition in FHR5 nephropathy is that under normal circumstances, there is activation of C3 within glomeruli." (PMID 33753502, 2021). "In human LN, the contribution of the alternative complement pathway to the development of kidney damage is supported by the observation that reduction in C3, but not C4, is associated with LN flare, and with the development of circulating anti-C3b antibodies." (PMID 33562189, 2021). "C3, in particular, is a key molecule of this system that can be produced locally and activated in the kidney, where its increased levels are usually seen as being related to nephropathies; however, even lower levels suggest intra-renal inflammation and have been related to poor renal outcomes." (PMID 40427671, 2025).
kidney damage (continued). "Notably, in CFHR5 nephropathy, serum C3 levels typically are normal." (PMID 22503529, 2012). "The prototypical example is CFHR5 nephropathy, through which an internal duplication within a single CFHR5 gene generates a mutant FHR5 protein (FHR5mut) that leads to accumulation of complement C3 within glomeruli." (PMID 33753502, 2021). "We observed elevated IgM and attenuated C3 in 93.8%% (15/16) and 81.3% (13/16), respectively, and these rates were significantly higher (P < 0.05) than the same indices in 48 children without nephropathy." (PMID 37667269, 2023). "Atypical membranous nephropathy (aMN) is a new type of nephropathy in China, characterized by a ‘full-house’ on immunofluorescent examination, that is IgG, IgA, IgM, C3, C1q positive, but without clinical evidence of a secondary cause." (PMID 35272568, 2022). "However, compared with children without nephropathy, those with CS nephropathy had reduced serum C3 levels and elevated IgM levels, suggesting the activation of the alternative complement pathway." (PMID 37667269, 2023). "Remarkably, the male hFH-FHR5mut phenotype recapitulated the key features of CHFR5 nephropathy: normal FH function, intact plasma C3 regulation, abnormal glomerular C3 deposition in the absence of IgG, and the development of electron-dense deposits within the GBM and mesangial matrix." (PMID 33753502, 2021). "In CFHR5 nephropathy, C3 levels typically are normal and C3NeF is absent." (PMID 24161036, 2013).
metabolic syndrome (36 papers, 2012 to 2025). A cluster of metabolic risk factors for CARDIOVASCULAR DISEASES and TYPE 2 DIABETES MELLITUS. "Cluster 5 (#4 activation) has 30 keywords, including c3 deficiency, oxford classification, metabolic syndrome." (PMID 37576817, 2023). "In the general population, increased levels of C3 and C4 have been associated with metabolic syndrome, a relationship underpinned by the fact that the adipose tissue can synthesize complement factors." (PMID 35242041, 2022). "Outside of pregnancy, elevated C3 complement concentrations (C3) are a risk factor for the metabolic syndrome (MetS), a condition characterised by dyslipidemia, elevated arterial blood pressure, abdominal obesity, and disordered glucose regulation." (PMID 34700074, 2022). "Complement activation, specifically factors C3, C4, C3a, Factor-H and Properdin, are associated with increased incident metabolic syndrome; and complement activation was related to adverse pregnancy outcomes, such as intrauterine growth retardation and GDM." (PMID 33859618, 2021). "Gestational Diabetes Mellitus (GDM) development is related to underlying metabolic syndrome that is associated with elevated complement C3 and C4." (PMID 33859618, 2021). "Many recent studies have reported that elevated complement C3 and C4 levels are risk factors for metabolic syndrome and cardiovascular diseases, while vitamin D is a protective factor." (PMID 32765534, 2020). "For example, higher complement 3 (C3) and complement 4 (C4) were associated with an increase in metabolic syndrome (MetS)." (PMID 31842750, 2019). "Several components of the alternative pathway (i.e., C3, C3a, FH, and properdin) as well as for one component of the classical pathway activation (C4) were significantly and positively associated with the metabolic syndrome." (PMID 30132263, 2018). "We also show that baseline concentrations of complement C3 and C4 were positively and significantly associated with development of the metabolic syndrome during the 7-year follow-up period." (PMID 30132263, 2018). "In conclusion, we herein report that complement C3 and C4 are positively associated with incidence of the metabolic syndrome." (PMID 30132263, 2018). "C3 (odds ratio (OR) = 1.48 [95% confidence interval: 1.02; 2.14]) and C4 (OR = 1.95 [1.32; 2.88]), but none of the other complement components were associated with incident metabolic syndrome (n = 40 cases)." (PMID 30132263, 2018). "PCOS, as one of the diseases that is associated with metabolic syndrome, also may have changes in inflammation factors such as C3,CRP, interleukin-6, tumor necrosis factor-a, and lipid profiles." (PMID 25904961, 2015). "While many studies have linked serum complement C3 and its cleavage products to type 2 diabetes, metabolic syndrome and cardiovascular diseases, and C3 levels are related to body fat, the underlying mechanisms explaining this association are still unknown." (PMID 24743347, 2014). "Also, activation of the C3–C3a–C3adesArg/ASP axis may provide a partial explanation for the observation that C3 is a risk factor for the development of the metabolic syndrome." (PMID 30132263, 2018). "An epidemiological design, consisting of cross-sectional (n = 2376) and cohort (n = 976) studies, was adopted to investigate the association between complement factors 3 (C3) and 4, and the metabolic syndrome (MetS) development." (PMID 26726922, 2016). "An elevated level of plasma C4, as well as C3, are reported as strong inflammatory indicators of metabolic syndrome, cardiovascular diseases, thrombotic diseases and allergic diseases." (PMID 35768780, 2022). "Previous researches revealed that the levels of serum C3 and C4 positively correlated with the development of the metabolic syndrome and had been identified as important markers relevant to this disease." (PMID 33194389, 2020). "Increased serum complement C3 has been related to body fat mass, metabolic syndrome and chronic diseases." (PMID 29299442, 2017).